CD44 (CD44 molecule (IN blood group))
Diseases named in the same sentence as CD44 in open-access papers (continued):
Sharing a sentence is not in itself a finding about the gene and the disease.
tumor (continued). "CD44+ and high-c-Myc-expressing tumor cells may represent cancer stem cells with possible involvement in metastasis, warranting further validation." (PMID 40395327, 2025). "Notably, CD44 is considered an early indicator of malignancy, and its isoform expression varies between normal and tumor cells, highlighting its roles in both physiological and pathological contexts." (PMID 40291275, 2025). "Moreover, we show that these EGFR‐high tumour cells overexpressed LGALS3, CD59, laminins (LAMB1 and LAMB3), PROS1 and so on that induced LAG3 and CD44 expression in the associated CD8+ T cells featuring an exhaustion state." (PMID 40621643, 2025). "Moreover, maintenance of cancer stem-like traits via miRNA-mediated stabilization of CD44 sustains tumor cell plasticity and drug evasion." (PMID 41008798, 2025). "The interaction between LGALS9 and CD44 may modulate tumor cell functions, as LGALS9 expression positively correlates with NK cell abundance while negatively correlating with neutrophils." (PMID 40747615, 2025). "Future studies might consider the percentage of CD44+ cells in individual tumor samples, establish a link with miRNA-21 concentrations, and correlate with clinical parameters." (PMID 39851519, 2025). "This delayed action could provide a crucial window for resveratrol to exert its sensitising effects on chemoresistant cell populations, such as CD44‐positive CSCs, or within the tumour microenvironment." (PMID 40888184, 2025). "Further modifications led to the creation of D4RA6H, designed from the DMBT1 sequence (GRVEVLXXXXW), with the “XXXX” motif replaced by an arginine-rich sequence (RRRR) for siRNA binding, and fused with a CD44-targeting moiety (KPSSPPEEHH) to increase tumour cell selectivity." (PMID 41129852, 2025). "Inhibiting both autophagy and NRF2 signalling simultaneously can increase the cytotoxic effects of cisplatin, diminish the proliferation of oral CD44+ cells and provide new possibilities for addressing chemoresistance and tumour recurrence related to oral cancer CSCs in clinical practice." (PMID 40665579, 2025). "HA expressed by mesothelial cells promotes tumor cell adhesion via [interactions with] CD44." (PMID 40369674, 2025). "Notably, CD44 serves as a receptor for LGALS9, with its expression in tumor and immune cells closely linked to tumor migration, invasion, and immune evasion." (PMID 40747615, 2025). "CD44 is also involved in cell proliferation and tumor angiogenesis." (PMID 39932626, 2025). "Furthermore, tumor cells detect extracellular HA in the tumor microenvironment through CD44 to regulate intracellular nucleotide sugar biosynthesis, affecting glycan metabolism." (PMID 41461315, 2025). "The rapid downregulation of miR-141, a tumor suppressor miR, by progesterone potentiated a progesterone-dependent increase in the CD44+ and CK5+ populations, suggesting that suppression of miR-141 helps maintain a more stem-like phenotype that drives the disease." (PMID 40244378, 2025). "We wondered whether the CD44+ tumor cells with high stemness gained the enhanced invasive and metastasis potential through a PTN-dependent and CAFs-associated manner." (PMID 40069574, 2025). "Interactions via the Cd44/Col14a1 and Cd44/Col1a1 pathways highlight the role of immune cells in monitoring the tumour microenvironment, which may be involved in modulating the inflammatory response and promoting tissue repair." (PMID 40046334, 2025). "Interestingly, CHI3L1 can be released into the tumor microenvironment (TME) and interacts with CD44 expressed on tumor-associated macrophages to activate the AKT pathway, thus contributing to M2 macrophage polarization." (PMID 39827337, 2025). "Two months after complete tumor regressions and cessation of treatment, the proportion of CD44 + CD62L− effector memory and CD44 + CD62L + central memory CD4 + and CD8 + T cells were higher in the blood of cured mice compared to treatment-naïve mice implanted with tumors." (PMID 40585246, 2025).
tumor (continued). "The HA gel shell can actively target CD44 expressed on tumor cells and depolymerize in response to the acidic TME and HAase, while TR@siSCD1 micelles can target PCa cells with the guidance of the RGD peptide and release siSCD1 in response to intracellular GSH and the proton sponge effect." (PMID 39736148, 2025). "Additionally, qPCR analysis demonstrated increased expression of interferon-γ and tumour necrosis factor-alpha (TNFα) in the tumours of the CD44-IR700_IT group when compared to the CD44-IR700_IV group." (PMID 39848206, 2025). "CD44 appears particularly significant as it holds particular importance due to its role in the WNT/β-catenin signaling pathway, which is frequently implicated in cancer stem cell regulation and tumor initiation." (PMID 40520180, 2025). "The interaction between CD44 and hyaluronic acid, a major component of the extracellular matrix, further stabilizes this protective niche, complicating the accessibility of targeted therapies to tumor antigens." (PMID 40075578, 2025). "CD44 is a cell surface glycoprotein, which is involved in cell–cell and cell–matrix interactions, with a key role in tumor biology, particularly in cancer stem cells (CSCs), influencing their self-renewal, differentiation, tumor initiation, metastasis, and therapy resistance." (PMID 40005368, 2025). "Immunohistochemistry was used to determine tumor cell proliferation using Ki-67 staining and to assess the expression of infiltration markers such as matrix metalloproteinase-2 and cell migration markers such as CD44." (PMID 40940872, 2025). "Moreover, CD62P (P-selectin) on the platelet membranes binds selectively to CD44 on tumor cells, enabling tumor-targeting capability." (PMID 40624508, 2025). "Therefore, the objective of this study was to examine the expression levels of miR-21 in OSCC tumor tissues, isolate CSCs (CD44+ cells) from the heterogeneous tumor populations, characterize them, and compare miRNA-21 expression between CD44+ and CD44− cells." (PMID 39851519, 2025). "The results suggest that CD44 is useful for assessing lymph node metastases and stratifying the degree of tumor differentiation, while ALDH1 may serve as a strong indicator of malignant transformation risk in OPMD." (PMID 40005368, 2025). "The photoimmunotheranostic effects against CD44‐expressing TNBC tumors have previously been reported using xenograft orthotopic TNBC murine models, whereby the putative therapy was able to selectively destroy CD44‐expressing tumors, thus enhancing tumor‐free survival." (PMID 40970572, 2025). "Therefore, ESRP1 has a significant impact on tumor occurrence, development, invasion, and metastasis by regulating the alternative splicing of CD44." (PMID 40046628, 2025). "Indeed, cross-talk between different members of the HER family and with CD44 or CD109 has been shown to influence tumour cell behaviour and progression." (PMID 40227788, 2025). "In vitro 2D and 3D antitumor effect evaluationsdemonstrated that AKPC-siYT encapsulating YAP/TAZ-siRNA specificallybinds to tumor cells with high CD44 expression and efficiently deliverssiRNA to these cells, resulting in apoptosis and growth inhibitionof tumor cells." (PMID 40176316, 2025). "Also, the overexpression of CD44 often exposes the tumor microenvironment to high levels of reactive oxygen species (ROS)." (PMID 40362259, 2025). "Targeting and blocking the SPP1/CD44 pathway has been shown to restore T cell function and inhibit tumor growth, suggesting that this pathway may serve as a promising therapeutic target for HCC." (PMID 40474968, 2025). "Among epithelial populations, we identified tumor cells (expressing Cd44, Ccnd1, Plau, Krt7), luminal alveolar (AV) cells (expressing Kit, Ehf, Csn3, Ltf), luminal hormone-sensing (HS) cells (expressing Prlr, Esr1, Pgr), and myoepithelial cells (expressing Myh11, Mylk, Myome1)." (PMID 41332581, 2025).
tumor (continued). "The CD44-HA axis is involved in a wide range of physiological and cancer-related processes, particularly in cell adhesion and migration, lymphocyte activation, as well as tumour progression and metastasis." (PMID 41155181, 2025). "To pinpoint the crucial factors mediating the interaction between PC cells and neutrophils, we analyzed intercellular communications involving ligand-receptor pairs and found that the SPP1 (tumor)–CD44 (neutrophil) signal was dramatically inhibited in the ZEB1 KD group." (PMID 40924501, 2025). "Furthermore, there was a significant association between the depth of tumor invasion and the expression of CD133+, CD44+/CD133+, CD166+/CD133+, and the combined CD133+/CD166+/CD44+ markers (p ≤ 0.05)." (PMID 41303421, 2025). "Finally, we compared the two main clusters of tumor cells: proliferating and CD44+ tumor cells, and found that c-Myc was one of the most significantly increased proteins in CD44+ tumor cells." (PMID 40395327, 2025). "Notably, PLC stem cells are characterized by high CD44 expression, making this receptor a compelling target for therapeutic strategies aimed at achieving tumor regression and reducing recurrence through the eradication of cancer stem cells." (PMID 40278256, 2025). "Notably, MIF played a crucial role in tumor immune responses through interactions such as MIF - CD74/CD44." (PMID 40036264, 2025). "Additionally, TGFβ expression has been identified as a downstream event of Cd44-dependent signaling, which is critical for tumor cell survival and the formation of metastatic colonies in the lung parenchyma of syngeneic mice." (PMID 40806360, 2025). "The downregulation of CD44 in established brain metastases supports a “hit-and-run” model, in which CD44 expression facilitates early colonization but is later downregulated as tumor cells adapt or evade immune surveillance." (PMID 40805225, 2025). "Additionally, a positive correlation was found between SIRI levels and the CD44+ tumor stem cell (CSC) score, with higher SIRI levels associated with an increased proportion of CD44+ CSCs." (PMID 40458729, 2025). "The inhibition of tumor migration by aptamers targeting exon v10 of CD44 has been confirmed." (PMID 41440277, 2025). "Because ALDH1+ CSCs usually reside in the center of the tumor, while CD44+/CD24− cells are found at the edge, and these cell phenotypes can transition between the types, sampling bias may have affected the results before and after treatment." (PMID 40869256, 2025). "Previous studies have described interactions between COL1A1 and CD44, which may relate to the regulation of stemness and invasiveness in several tumor types." (PMID 40851082, 2025). "In vivo, IC-2 reduced tumor growth in mice xenografted with CD44-positive HuH7 cells." (PMID 40890130, 2025). "We combined flow cytometry, LEGENDplexTM immune profiling, and preoperative/postoperative serum cytokine analyses to determine checkpoint molecules (e.g., PD-1, TIM-3, LAG-3), immune cell profiles, as well as key markers on tumor cells (CD44, PD-L1, MHC class I/II)." (PMID 40860824, 2025). "CD44 actively participates in the process of tumor metastasis." (PMID 39851489, 2025). "Moreover, tumor stemness was assessed by analyzing the expression of stemness markers, including CD44 and CD133." (PMID 41209698, 2025). "We found that Sox2‐ and CD44‐positive GSCs remained present at unresected residual GBM tumor sites." (PMID 39721005, 2025). "This reduces CD44-mediated migration and metastasis, helping to limit tumor spread." (PMID 40270603, 2025). "In addition, we performed immunohistochemistry experiments on BC tissues at different stages and found that with the progression of BC, the expression levels of tumor stemness-related markers (CD44, OCT4, SOX2, NANOG) gradually increased." (PMID 41387479, 2025).
tumor (continued). "This could also indicate that more molecules can influence BRCA1 function in the tumor microenvironment, and CD44 as main HA receptor could be the link between HA metabolism and the DNA repair process in tumors." (PMID 41373491, 2025). "This suggests that while A6 has been reported to enhance tumour selectivity via CD44 interaction, its integration into CPP backbones may interfere with the structural requirements for siRNA complexation." (PMID 41129852, 2025). "Transmembrane protein Cluster of differentiation 44 (CD44) is considered the main HA receptor, and their interaction can control different cellular functions like adhesion and migration which can, in turn, influence tumor development." (PMID 41373491, 2025). "Similarly, the patients with a low CD3+ TIL density and a high CD24/CD44 coexpression in tumor cells had the worst DFS, MFS, and OS, with a median of 3.9 years for both DFS and MFS." (PMID 40647395, 2025). "Moreover, we found that increased expression of CD44 in ccRCC patient samples was correlated with tumor grade." (PMID 39815326, 2025). "This differential expression raises the possibility that HPV oncoproteins may influence CD44 regulation, potentially by activating EMT‐associated transcription factors or modulating the tumor microenvironment." (PMID 40888184, 2025). "Optimized assays for the isolation of the putative stem cell population include the isolation of tumor spheroids, the sorting of cells positive for cell surface protein expression, such as CD44 and CD133, and the isolation of cells resistant to chemotherapeutics." (PMID 40141171, 2025). "We developed an experimental methodology to induce tumor cell dormancy that enabled the characterization of features associated with poor prognosis and recurrence after treatment, such as the emergence of the CSC marker CD44." (PMID 40430044, 2025). "We also detected tumor stem cells by staining CD44 and Lgr5 markers." (PMID 40611658, 2025). "ITGB1 is related to stemness and coexpressed with stem cell markers such as OCT4 and CD44 in tumor cells, whereas its prognostic role remains unclear." (PMID 40287842, 2025). "Altered CD44 expression, including the presence of specific alternative isoforms (e.g., CD44v6), correlates with increased tumor aggressiveness and a poorer clinical prognosis in numerous types of cancer, including colon, breast, and gastric cancers, as well as leukemias." (PMID 41009438, 2025). "Low expression of IL‐11 in tumour cells was associated with significantly higher levels of leukocytes (CD45), T cells (CD3, CD4, CD8), T‐cell activation (CD44, CD25, ICOS, Tim3), dendritic cell activation, antigen presentation (CD11c, CD80, B2M, HLA‐DR) and macrophage (CD68) markers." (PMID 40673604, 2025). "Some types of cancer cells express hyaluronan synthases (HAS1, HAS2, and HAS3), as well as fibroblasts and chondrocytes as part of the extracellular matrix, and the signaling between HA and CD44 is deemed critical for tumor proliferation and the spread of cancer." (PMID 40011711, 2025). "Moreover, OC cells excessively produce PAI-1 and DLX4, which trigger IL-8/CXCL5 and IL-1b/CD44 expression via NF-kB signaling in CAMs, intensifying tumor-cell interactions and metastasis." (PMID 40369674, 2025). "CD44 is recognized as a marker of tumor-initiating cells across various tumors, including BC." (PMID 40443562, 2025). "This dual functionality highlights that the clinical significance of CD44 is highly context-dependent, where its loss, rather than its presence, can be a key indicator of aggressive tumor behavior leading to poor patient survival." (PMID 41514534, 2025). "Among these, CD44 is widely recognized for its high expression in CSCs from multiple tumour types." (PMID 41321388, 2025). "Finally, the subcutaneous tumour experiment results also showed that silencing HEY1 inhibits the growth of OS through the CD44/EGFR/FAK pathway." (PMID 40531089, 2025).
tumor (continued). "Modulating the splicing of CD44 could inhibit tumor invasion and metastasis, making ESRP1 or specific CD44 splice variants potential targets for cancer therapy." (PMID 40046628, 2025). "Additionally, CD44 signaling influences the tumor microenvironment by modulating immune evasion and angiogenesis." (PMID 40867277, 2025). "Aldometanib did not affect the numbers of stem-like CD8+ T cells (PD-1+CD44+Tim3−Tcf7+) or terminally exhausted CD8+ T cells (CD8+ Tex; PD-1+CD44+Tim3+Tcf7−), indicative of the presence of long-lasting anti-tumor immunity and an effective immune surveillance mechanism." (PMID 41286115, 2025). "Interestingly, CD44 is also a surface marker of cancer stem cells (CSCs), the subpopulation of tumor cells endowed with stem-like properties that promote tumor initiation, invasive growth, and metastasis formation." (PMID 40259212, 2025). "Moreover, according to the CD44 role in enhancing tumor cell aggressiveness by promoting stem-like plasticity, 24 h treatment of Cis-Pt-R cells with HA (50 μg/mL, 180 kDa) induced the formation of tubule-like structures." (PMID 40342488, 2025). "However, the regulation of CD44 overexpression at the leading edge within the BrCa tumor mass remains largely unexplored." (PMID 40409554, 2025). "Additionally, studies have demonstrated that SPP1 macrophages can bind to CD44 on the surface of T cells, thereby suppressing their anti-tumor function." (PMID 40474968, 2025). "Levels of the transmembrane glycoprotein CD44 have been repeatedly reported to predict poor patient prognosis, and cells expressing high levels of CD44 were shown to have higher invasion and migration abilities and higher expression levels of pluripotency markers than the bulk of the tumor cells." (PMID 41228340, 2025). "Finally, our results suggest that SPC-high cells exhibit considerable plasticity and possess the potential to give rise to CD44-high cells during tumor progression." (PMID 39930268, 2025). "Finally, we identified two distinct subclusters of tumor cells: proliferating cells and CD44-positive tumor cells." (PMID 40395327, 2025). "We performed IHC staining to investigate the expression of Sox2 and CD44 in tumor tissues." (PMID 39721005, 2025). "We further assessed whether ALK+ tumor cells expressing CD4 or CD8 also expressed CD44 or CD62L markers, usually used to distinguish naïve (CD62Lhigh CD44low), effector (CD62Llow CD44high) or central memory T cells (CD62Lhigh CD44high)." (PMID 40175628, 2025). "CD44 variant isoforms are critical for CSC maintenance and tumor progression." (PMID 40363706, 2025). "Despite the obvious prospects of hyaluronic acid-based drugs as the main ligand for CD44 in antitumor therapy, its effectiveness may depend on which CD44 isoform is expressed in tumor tissue." (PMID 39851489, 2025). "OHA has the ability to bind specifically to CD44, an activated cell surface glycoprotein, and could actively target tumor tissue and be internalized by cancer cells via CD44-mediated endocytosis." (PMID 40284532, 2025). "However, certain PLC cell lines, such as SK-HEP-1, demonstrate high CD44 overexpression, which is correlated with increased tumor invasiveness and recurrence rates." (PMID 40278256, 2025). "Interestingly, impaired FXa-PAR2 signaling also affected the phenotype of contaminating Cd44/Epcam+ tumor cells (cluster 16)." (PMID 40694429, 2025). "Research indicates that CD44 knockdown (CD44kd) in prostate cancer xenografts significantly reduces tumor growth rate after continuous docetaxel treatment compared with control cells, suggesting that the combination of chemotherapy with CD44kd can lead to a beneficial chemotherapy outcome." (PMID 40114966, 2025). "The study concluded that the differential expression and shedding of CD44 isoforms might play crucial roles in tumor metastasis and immune evasion." (PMID 41440277, 2025).